IL10 (interleukin 10)
Diseases named in the same sentence as IL10 in open-access papers (continued):
Sharing a sentence is not in itself a finding about the gene and the disease.
infection (continued). "Neither IL-4 nor IL-5 was detected and high levels of IL-10 (1661±341 pg/ml) were maintained after infection." (PMID 25144756, 2014). "The contribution of the surrounding liver tissue, however, was quite significant for other ones, e.g. IL-12, IFN-γ, IL-4 and IL-17A, at the early stage of infection; CXCL9, IL-4, IL-5, CCL17, at the middle stage; and IL-10 and TGF-β at the late stage of infection." (PMID 24637903, 2014). "In addition, in mice infected with nonlethal strains of P. yoelii, the presence of cytokines such as IL-10 and TGF-β during the chronic phase of infection was detected." (PMID 25276830, 2014). "In addition, over the course of these infections, DCs reduce levels of CD11c, increase expression of CD45RB, and promote the generation of T cell IL-10 production." (PMID 25352846, 2014). "Cytokine storm is characterized by abundant release of pro-inflammatory cytokines, such as IFN-γ, TNF-α and IL-6, as well as the anti-inflammatory cytokines such as IL-10; however, its mechanism of induction in oriential infection is not totally understood." (PMID 25254971, 2014). "Therefore, we evaluate the levels of BAL and serum IL-6, IFN-β and TNF-α on day 2 post-infection and the concentrations of IFN-γ and IL-10 on day 5 after challenge." (PMID 23947615, 2013). "In our study the IL-10 levels in lung homogenates were significantly lower in the pEGFP/Ag85A-HA2 vaccinated group and the iPR vaccinated group than those of other groups at day 2 after infection with S. aureus (P < 0.05)." (PMID 23369570, 2013). "During infection with Mtb, IL-10 is primarily produced by infected and non-infected macrophages, with smaller quantities arising from regulatory T cells." (PMID 23869227, 2013). "For the lung-LN response, only the IFN-γ levels showed a significant increase at the latest time point of infection compared to the NI level (p = 0.036); there was no change in IL-4 or IL-10 over the infection period." (PMID 24086786, 2013). "We believe that a direct effect of IL-10 on virus production is rather unlikely as we have seen in our in vivo kinetics of viral loads that differences between C57BL/6 and Il-10−/− mice only become apparent after day 6 of infection." (PMID 24244162, 2013). "New data indicate that L. mexicana parasite loads do not increase early in infection, but only increase later once the IgG1-induced IL-10 is present (Jude Uzonna, University of Manitoba, personal communication)." (PMID 23675550, 2013). "As αCD25 depletion did not decrease IL-10 mRNA levels on day 2 post infection, natural Tregs do not seem to be relevant IL-10 producers during LCMV infection." (PMID 24244162, 2013). "As depletion of monocytes/macrophages decreased the levels of IL-10 mRNA on days 2 and 5 post infection, while αLy6G depletion failed to do so, it is likely that monocytes/macrophages are the relevant IL-10 source rather than neutrophils." (PMID 24244162, 2013). "In the spleens, similar to the JaOArS982 infection, the levels of IFN-γ, IL-2 and IL-4 in IL-10 KO and TNF-α KO mice were significantly increased compared with those of WT mice at 7 days pi following JaTH160 infection, whereas the level of IL-5 was decreased in TNF-α KO." (PMID 23940775, 2013). "In this study, expression levels of IL-4, IL-10, IL-13 and TNF-α were significantly up-regulated while the expression levels of IL-1β,IL-18,IFN-γ, IL-2, IL-15, IL-17F, IFN-α, IFN-β, IL-3 and CSF-1 were markedly decreased in PBMCs at all stages of infection." (PMID 24358317, 2013). "By contrast, at 7 days post infection, the levels of CCL2, CCL3, CXCL2, IFN-γ and the anti-inflammatory cytokine IL-10 were significantly lower in influenza A virus-infected Nox1−/y lung compared to WT control, whereas IL-β, IL-6, TNF-α, and GM-CSF were similar between the two strains of mice." (PMID 23577160, 2013). "Virus-infected mice that recovered from KY/136E infection showed a high IL-10 response by 6 DPI whereas KY/180E-infected mice showed no response (p<0.05)." (PMID 23441208, 2013).
infection (continued). "Following infection with L. major, the T cell-specific IL-10 mutant BALB/c mice displayed a healing phenotype, indistinguishable from the complete IL-10-deficient BALB/c mice." (PMID 23825956, 2013). "The data revealed that infection with Ad-MGBA improved DC maturation and up-regulated the expression of co-stimulatory molecules and the secretion of interleukin-12 (IL-12), but down-regulated interleukin-10 (IL-10) secretion from DCs." (PMID 23650543, 2013). "In a BALB/c IL-10−/− mouse model, however, the observed resistance to infection was attributed to the absence of IL-10 secreted by macrophages." (PMID 23825956, 2013). "Consumption of L. casei prior to infection failed to increase anti- inflammatory molecules such as IL-10 and TGF-β in the intestine." (PMID 24340048, 2013). "Contact-dependent, synergistic interactions have not previously been reported for IL-10 responses during infection." (PMID 24155979, 2013). "However, infection with MVA or NYVAC induced the expression of IL-6, TNF-α and IL-10, being this induction higher in KO mice." (PMID 24244156, 2013). "In accordance with the literature, absence of CD11c+ cell-derived IL-10 resulted in strongly decreased overall IL-10 mRNA levels on day 2 and 5 post infection in the spleen." (PMID 24244162, 2013). "The macrophage/neutrophil-specific IL-10-deficient mice on a C57BL/6 background never showed any significant difference in disease progression compared to IL-10-competent control mice, neither early after infection nor at any later time point." (PMID 23825956, 2013). "Interestingly, O'Leary and collaborators have demonstrated that IL-10 production by immune cells can affect the ability of M. tuberculosis to escape the LAMP1+ late endosomal compartment and to establish infection in human macrophages in vitro." (PMID 23818855, 2013). "In late stages of infection, IL-10 production was unaffected by the absence of TbKHC1, while NO production (and iNOS expression) was lower when TbKHC1 was present." (PMID 24204274, 2013). "Several cytokines, such as the granulocyte macrophage colony-stimulating factor (GM-CSF), IL-1α, TNF-α, IL-10, IL-17A, IL-2, IL-4 and IL-5, showed a slight but non-significant increase in their serum concentrations upon infection (data not shown)." (PMID 23776551, 2013). "Also, an iRBC infection induces production of the pro-Treg cytokines TGF-β and IL-10 by DCs, which are close to T cells within the spleen." (PMID 24312297, 2013). "To assess the role of endogenous IL-10 in TGF-β1 expression and secretion during Brucella abortus infection, we performed real-time PCR and ELISA in spleen cells from infected mice at 1, 2, 3 and 6 weeks post-infection." (PMID 24069337, 2013). "Lastly, at later stage of infection lack of IL-10 leads to increased number of Treg cells and TGF-β1 production which coincides with reduction in liver pathology." (PMID 24069337, 2013). "On the other hand, when cPLA2 was blocked 1 h before the infection by treatment of macrophages with cPLA2 antagonist ATK (gray bars), proinflammatory cytokines TNF-α, IL-1β, and IL-6 were upregulated; furthermore, IL-10 expression was significantly affected when cPLA2 was inhibited." (PMID 23555077, 2013). "In dogs at the late stage of infection with T. cruzi characterized by the absence of heart damage, high levels of IL-10 in the serum and supernatants of peripheral blood mononuclear cells have been observed." (PMID 23497041, 2013). "We see similar results for the balance of TNF-α and IL-10 in a granuloma at all time points beyond ∼75 days post-infection (data not shown)." (PMID 23869227, 2013). "A previous study also demonstrated that IL-10 produced by Th1 cells is critical in preventing immunopathologies in various infection models and represents a negative feedback mechanism that is independent of Treg cells." (PMID 23696838, 2013). "We showed that the presence of B-cells conferred a basal level IL-10 response regardless of infection." (PMID 24155979, 2013).
infection (continued). "Upper compartment infection of uroepithelial cell monocultures resulted in no significant IL-10 levels." (PMID 24155979, 2013). "The data reported here is limited to a single time point of 24 hpi so changes in IL-10 mRNA levels occurring earlier after infection would not have been detected." (PMID 23347398, 2013). "Thus, DCs and monocytes/macrophages account for a first wave of IL-10 production, followed by a second wave of IL-10 production by DCs, CD4+ T cells and monocytes/macrophages on day 5 post infection." (PMID 24244162, 2013). "No IL-10 was seen when cells were unstimulated and when infection with LCL-opsonized amastigotes was not accompanied by LPS stimulation." (PMID 23675550, 2013). "In contrast, TNFα, CD80 and A3Z1 and IL-10 expression did not increase upon infection with most of the strains." (PMID 24070317, 2013). "We also observed a high production of IL-10 ninety days after infection with a slight increase through time, but the levels were not significantly different between the time points evaluated." (PMID 23577121, 2013). "In the very first week after infection the vaccinated mice produced less than half the amount of IL-10 and IL-4 compared to the non-vaccinated mice." (PMID 23825956, 2013). "The importance of macrophage derived IL-10, secreted following IgG-FcγR engagement, is further called into question by the finding that mice lacking IgG1 are more resistant to infection with L. mexicana." (PMID 23825956, 2013). "In line with one of our findings (data not shown), Th1 cells were reported as the source of IL-10 in Plasmodium chabaudi chabaudi AS infection to protect mice from pathology during acute phase." (PMID 23724100, 2013). "The infection may lead to activation of monocyte/macrophage lineage and expression of interleukin-6 (IL-6), interleukin-10 (IL-10), and tumour necrosis factor-alpha (TNF-α) the serum levels of which have been correlated with the severity of the infection." (PMID 23983770, 2013). "Therefore, IL-10 inhibits disease and inflammation in mice infected with RSV, especially during recovery from infection." (PMID 22393401, 2012). "However, when combining the factors identified by the multiple logistic regression analyses, we found the combination of elevated IL-10 and IP-10 levels with decreased RANTES levels to be predictive of infection, with the highest AUC of 0.83." (PMID 23155405, 2012). "Such mice also display enhanced resistance to infection with L. donovani, although T cell IL-10 production was not assessed." (PMID 22911108, 2012). "The absence of IL-10 did not affect viral load in the lung on day 4 post infection, the time of peak of viral load." (PMID 22393401, 2012). "Both EV71 and CVA16 caused significant increases in IL-6 and RANTES mRNA levels; on the other hand, IL-10, NF-κB p65 and IL-1α were not elevated in RD cells 8 h after infection." (PMID 22666293, 2012). "In our previous results we observed that praziquantel downregulated the IL-4, modulates IFN-γ production, and increased IL-10 production in spleen cells with 120 days of infection (data not shown)." (PMID 22623908, 2012). "Further, C57BL/6 mice exhibited higher levels of placental IL-10 production that did not significantly dissipate in the presence of infection." (PMID 22952869, 2012). "The expression of the Th2 cytokine IL-4, the Th17 cytokine IL-17, as well as of IL-10, was low and did not vary during infection regardless immunization." (PMID 22413022, 2012). "Despite the increased immune responses and pathology during infection in the absence of IL-10, viral titers in the IL-10−/− livers remained comparable to those in WT livers at all time points analyzed." (PMID 22880122, 2012). "The levels of myeloperoxidase (as neutrophil marker), TNFα, INFγ, GM-CSF, IL-1β and IL-6 transiently increased in lungs after infection, while levels of IL-10, IL-17A and IL-22 were indistinguishable from PBS controls." (PMID 22319619, 2012).
infection (continued). "We did not detect IL-10 release in response to Udorn-infection in either Mph1 or Mph2 of any donor (n = 6; data not shown)." (PMID 22238612, 2012). "Like NK cells, the numbers of F4/80+ CD11b+ monocyte/macrophages were also increased on day 7 following infection in the absence of IL-10." (PMID 22880122, 2012). "Interestingly, BM-induced the anti-inflammatory cytokine, IL-10, in ATII cells and macrophages at 6 h post-infection, with delayed induction of inflammatory cytokines at 24 h post-infection." (PMID 23293773, 2012). "During T. cruzi infection, uncontrolled immune response has been proven to be deleterious to the host, as is the case of infection in the absence of IL10." (PMID 22348160, 2012). "IL-10 is not detected in serum and its corresponding transcript only appears after 3 days of infection." (PMID 22500859, 2012). "At 2 and 4 hours post infection, detectable levels of IL-10 were also present but this was not statistically significant." (PMID 23284947, 2012). "A role of IL-10 for promoting virus persistence has also been show in chronic LCMV Clone 13 infection, where the absence of IL-10 led to virus clearance and restored functionality of LCMV-specific CD8 T cells." (PMID 22876184, 2012). "In vivo we observed a relatively enhanced production of the pro-inflammatory cytokines TNFα and IFNß but not for the anti-inflammatory cytokine, IL10, with MCMVdie1 infection." (PMID 22952450, 2012). "Several immune cell types, including tolerogenic DCs, myeloid suppressor cells, IL-10-producing CD4+ T cells, B cells and Foxp3+ T regulatory cells, have confirmed roles in the modulation and inhibition of inflammation in the context of infection." (PMID 22563306, 2012). "More particularly ELISA assays indicate that Treg cell cytokine pattern (IL-2, IFN-γ, TGFβ and IL-10) remains unchanged after 48 h of infection (data not shown)." (PMID 22359669, 2012). "Interestingly, IL-10−/− mice exhibited decreased frequencies of both IFN-γ+ and TNF-α+ CD8+ T cells on day 7 post infection." (PMID 22880122, 2012). "The infection of DCs by Brucella triggers neither IL-12 nor IL-10 production whereas E. coli LPS treatment triggers both IL-12 and IL-10 production." (PMID 22928003, 2012). "Expression of TNFα, IL1b, IFNγ, TGFβ and IL10 was still significantly upregulated in the infected animals compared to the non-infected 7 days after infection." (PMID 22815907, 2012). "Although IFN-γ and IL-10 can be produced by many cell types, includingB cells, macrophages, and CD4+ or CD8+ T cells, the CD4+T cell mediated immune response plays a central role in the control of schistosomaafter natural infection or vaccination." (PMID 22802961, 2012). "We therefore first determined the levels of a panel of markers (IL-1β, IL-6, IL-8, IL-10, IL-12p70, TNF, RANTES, MIG, MCP-1, IP-10, IFN-α, IFN-γ, Ang-1, Ang-2, uPAR and VEGF R1/Flt1) in the plasmas of 79 women who remained infection-free from inclusion through to delivery." (PMID 23155405, 2012). "An increase in IFN-γ levels and a decrease in IL-10 levels were found in the intestinal mucosa of PI-IBS patients, suggesting that the infection may affect the Th1/Th2 balance." (PMID 22816602, 2012). "In the present study, we demonstrate that SAV-3 infections induce mRNA transcripts of genes including IFN-α and its stimulated genes (ISG) at early time, followed by IFN-γ, TNF-α, IL-12, IL-10, IL-8, CD3ε, CD4, CD8, TCR-α, MHC-I, and MHC-II as the infection progresses." (PMID 23116479, 2012). "Consistently increased concentrations in relation to infection, regardless of gestational age, were only seen for IL-10 and IP-10." (PMID 23155405, 2012). "Infection with the pathogenic Romero strain of JUNV has been reported not to induce measurable levels of IFN-β, IFN-α, TNF-α, IL-10 or IL12, in primary human monocytes and macrophages." (PMID 22629479, 2012). "The average IL-10 plasma levels of the CD4+ T cell-depleted group increased after infection as in the non-depleted group." (PMID 22533922, 2012).
infection (continued). "Concerning the immuno-modulatory cytokines, the IL10 signaling was among the pathways apparently triggered by the infection: a SOCS3-like transcript and Arginase-2 were up-regulated, suggesting that the expression of IL10 itself could be affected." (PMID 22720048, 2012). "Of note, following antibiotic treatment gnotobiotic IL-10−/− mice displayed neither any clinical nor immunopathological signs of large intestinal inflammation prior infection." (PMID 22808254, 2012). "When treated with APS (200 μg/ml) for 24 h ex vivo, the intranuclear Foxp3 protein, Foxp3 mRNA expressions and IL-10 secretion of CD4+CD25+Tregs isolated from burn plus infection mice on PBD 3 and 7 were obviously lower than those in untreated burn plus infection mice on PBD 3 and 7 (P<0.05)." (PMID 21698274, 2011). "In the present study, there was a rapid shift from a Th1 immune response characterised by the expression of IFNγ and IL-1β genes to a regulated Th2 immune response characterised by the expression of IL-13, IL-10, TGFβ, and FOXP3 genes by seven days post infection (dpi) in the carrier lambs." (PMID 21385411, 2011). "Further, IL-6 and IL-10 production were shown to be dependent on productive infection, while TNF-α production was not." (PMID 21572983, 2011). "Moreover, we indicated nDens of 2 genes induced and 2 genes repressed in all infection performed and nDens of all genes discussed above (IL-1β, IL-6, IL-12, TNF-α, IL-10, ADAM19, CCR7, CCL20 and IL-18)." (PMID 21436989, 2011). "During the later stages of infection when high level virus replication was noted in non-immunized mice, the host upregulated expression of IL-10 to counteract severe inflammation of tissues." (PMID 21949840, 2011). "More than likely, other immunological mechanisms of immune regulation (e.g. IL-10, APC dysfunction, in utero tolerization) may play a more prominent role in children (or in more recent infection)." (PMID 21559422, 2011). "The increased mortality seen in mice during the absence of IL-10 is not a result of the uncontrolled growth of the bacteria but rather that of unregulated immune responses to the infection." (PMID 21931790, 2011). "The lung cell IL-10 production was significantly higher in BCG-vaccinated/rHBHA-boosted mice (1955 ± 275 pg/mL) than in non-boosted (252 ± 42 pg/mL) and in control mice (68 ± 7 pg/mL) after i.n. infection." (PMID 21647410, 2011). "On the other hand, and similar to B6 animals, AKR/J mice had undetectable levels of IL-10 even 48 h post-infection and no statistically significant increase in concentrations of IL-6, TNF-α, MCP-1 or KC." (PMID 21533108, 2011). "We show that Treg numbers were not changed by infection, and TGF-β and IL-10 expression in the lung, which are involved in the suppression of inflammation by Tregs, were reduced by infection in AAD." (PMID 21998577, 2011). "Infection induces transcriptional changes in airway CD4+ T cells, including the up-regulation of a panel of inflammatory chemokines and cytokines, as well as the anti-inflammatory cytokine IL-10." (PMID 21647373, 2011). "In knock-out (KO) mice for the interleukin-10 (IL-10) gene (IL10-/-), the extent of the inflammatory infiltrate around the NC was markedly increased compared with control mice during the acute phase of infection, though the cellular composition remained the same." (PMID 21429196, 2011). "In untreated rabbits, most of these genes were progressively induced by Mtb infection from 4 to 8 weeks, and many had reached a plateau (IFN-γ, IL13, IL6, MIF, CCL4, NFκB, APRIL, TLR2, RAB7 and LAMP2) or were even reduced (IL10, CXCR3, GMCSF and PI3K3) by 12 weeks post-infection." (PMID 21949656, 2011). "Notably, infection decreased the expression of TGF-β and IL-10 in lung tissue in infected, allergic groups compared to uninfected, allergic controls." (PMID 21998577, 2011).